CCL20 (C-C motif chemokine ligand 20)
Diseases named in the same sentence as CCL20 in open-access papers (continued):
Sharing a sentence is not in itself a finding about the gene and the disease.
prostate carcinoma (continued). "In addition to PC3 cells, we tested the effect of CCL20 activation on biological function of other human prostate cancer cell lines - LNCaP, 22RV1 and DU145 cells." (PMID 19340288, 2009). "In a prostate cancer study, tumor cells can induce TAM infiltration and M2 polarization via the CCL20/CCR6 axis, leading to tumor progression." (PMID 38600588, 2024). "As with the expression level of CXCL8, CCL2, CXCL10, and CCL20, the number of Pref-1 or CD29 positive cells was increased in prostate cancer tissues with high Gleason scores of ≥8." (PMID 32971847, 2020). "CCL20/LARC expression is increased in response to cycling hypoxia in the SK-OV-3 ovarian adenocarcinoma cell line and PC-3 prostate cancer cell line." (PMID 32781743, 2020). "Immunohistochemical analysis of human normal and prostate cancer tissue array consistently demonstrated the increased expression of CXCL8, CCL2, CXCL10, and CCL20 in prostate cancer tissues." (PMID 32971847, 2020). "Among the four prostate cancer cell lines studied, only PC3 cells secreted detectable levels of CCL20 into the culture supernatant during the 48 hours incubation." (PMID 19340288, 2009). "In order to determine the role of CXCR4 in the regulation of CCL20 production, we silenced CXCR4 by RNA interference in PC3-CXCR4.5 - prostate cancer cells with high CXCR4 expression." (PMID 19340288, 2009). "Similarly, prostate normal epithelial cellsproduce the chemokine CCL20 and the expression of its receptor(CCR6) in prostate cancer cells has been recently found tobe a predictor of tumour aggressiveness." (PMID 21479216, 2011). "Furthermore, we found that CXCR4, CCL20 and CCR6 are over- and coexpressed in human prostate cancer specimens." (PMID 19340288, 2009). "In addition, expression of CXCL8, CCL2, CXCL10, and CCL20 was also increased in prostate cancer tissue induced by intraprostatic injection of LNCaP cells stably transfected with SFMBT2 shRNA and in the tissue of prostate cancer patients." (PMID 32971847, 2020).
esophageal cancer (16 papers, 2019 to 2026). A primary or metastatic malignant neoplasm involving the esophagus. "Serum CCL20 level was also shown to be increased markedly in patients with esophageal cancer, and was associated with cancer occurrence and metastasis." (PMID 33123272, 2020). "CCL20/chemokine signaling has also been previously implicated in esophageal cancer." (PMID 35164838, 2022). "For instance, FOXO1 promotes macrophage recruitment and M2-like macrophage polarization by enhancing the secretion of CSF-1 (colony-stimulating factor 1) and CCL20 (chemokine ligand 20) in esophageal cancer." (PMID 38714539, 2024). "CCL20, on the other hand, is over-expressed in esophageal carcinoma, and it has been shown to have a poor prognosis when its expression increases; in general, a crucial role of CCL20 has been demonstrated in tumor malignancy." (PMID 35163455, 2022). "Another study showed that CCL20 was upregulated in F. nucleatum-positive esophageal cancer patients." (PMID 33681225, 2021). "The chemokines CCL4 and CCL20 have been shown to recruit subsets of T cells in esophageal carcinoma, where CCL4 expression was correlated with the expression of CD8 and GZMB." (PMID 30451357, 2019). "CCL20 was selected based on previous studies demonstrating its increased expression (approximately 1.8-fold) in OSCC samples and its association with Fusobacterium colonization in esophageal cancer." (PMID 40869423, 2025). "Fusobacterium nucleatum mainly inhabits the oral cavity and causes periodontal disease, which may promote the aggressive behaviors of tumors by activating chemokines (e.g., CCL20) in esophageal cancer tissues." (PMID 34819887, 2021). "In addition, C-C Motif Chemokine Ligand 20 (CCL20), which plays crucial roles in cell proliferation and migration, is significantly upregulated in F. nucleatum-positive esophageal cancer tissues." (PMID 32867334, 2020). "Esophageal cancer cells promote macrophage M2 polarization and recruitment through up-regulation of CSF1 and CCL20, respectively." (PMID 38600588, 2024).
liver fibrosis (16 papers, 2015 to 2025). "These genes are known to gradually increase upon NASH progression, with Gdf15 and Ccl20 encoding proinflammatory cytokines, Col1a1 and Col1a2 encoding collagen chain proteins, and Itgbl1 known for regulating liver fibrosis." (PMID 37914694, 2023). "This was followed by the findings that CCL20 hepatic RNA expression and serum levels were increased in patients with alcoholic hepatitis and were associated grade of hepatic fibrosis." (PMID 29690903, 2018). "C-C motif chemokine ligand 20 (CCL20) is widely distributed across liver tissues and its over-activation can accelerate hepatic fibrosis by promoting hepatic inflammatory response." (PMID 40356603, 2025). "Involved in the immune-inflammatory response in the liver, promotes the expression of the pro-inflammatory chemokine CCL20 aggravates liver inflammation and promotes hepatic fibrosis." (PMID 39995661, 2025). "Upregulated CCL20 expression has been observed under conditions of hepatic fibrosis in patients with chronic liver diseases, such as hepatitis C virus infection, alcoholic steatohepatitis or primary biliary cirrhosis and in patients with MASH." (PMID 37686029, 2023). "Persistent hypermethylation of the ZNF154 and ZNF540 genes, as well as CCL20 hypomethylation, were registered in tumor tissue in relation to both liver fibrosis and liver cirrhosis." (PMID 36923478, 2023). "Emerging evidence confirms the key roles of CCL20 in various fibrotic processes, including cardiac and liver fibrosis." (PMID 35485286, 2022). "Because HSCs are key players in the development of liver fibrosis, we investigated the biological effect of CCL20, which is secreted from visfatin-treated macrophages, on LX-2 cells." (PMID 32418112, 2020). "CCL20 is a key molecule involved in the homing of dendritic cells, which have been shown to play a key role in liver fibrosis in animal models." (PMID 29690903, 2018). "Circulating CCL20 protein levels in serum were found to be significantly increased in patients with liver fibrosis." (PMID 29690903, 2018). "CCL20 serves as a chemoattractant molecule for immature dendritic cells, which have been shown to produce many of the inflammatory molecules that mediate liver fibrosis." (PMID 29690903, 2018). "In vivo studies confirmed that activation of TLR3 in HSCs by exosomes derived from damaged hepatocytes exacerbates liver fibrosis by enhancing the production of chemokine (C-C motif) ligand 20 (CCL20) and interleukin-17A (IL-17A)." (PMID 30469540, 2018). "This suggests that blocking IL-36 signaling can mitigate liver inflammation by decreasing CCL20 expression and, consequently, may intervene in the progression of liver fibrosis." (PMID 39995661, 2025). "Conversely, when IKK2 is superactivated in fasting liver or neonatal liver, where IKK1 is low and FOXO1 activity is high, FOXO1 synergizes with p65/p50 to cause insulin resistance and induce proinflammatory IL-1β, IL-6, CCL2, and CCL20, resulting in progressive inflammation and/or liver fibrosis." (PMID 26219821, 2015). "In HBV-related liver fibrosis (HBV-LF), the high expression of CCL20 may be closely related to the infiltration of immune cells in the liver and inflammatory responses, thereby affecting the occurrence and development of liver fibrosis." (PMID 41586310, 2025). "However, the mechanism of CCL20 in hepatic inflammation and liver fibrosis is unclear." (PMID 32418112, 2020). "Therefore, CCL20 induced by palmitic acid or LPS is involved in liver fibrosis." (PMID 32418112, 2020). "We hypothesized that visfatin, an adipocytokine, could play a role in hepatic fibrosis via CCL20." (PMID 32418112, 2020). "We hypothesized that visfatin could play a role in hepatic fibrosis via CCL20." (PMID 32418112, 2020). "From these data, we aimed to investigate the possibility of IL-34, M-CSF, sCD163, MIP-3α/CCL20, hyaluronic acid, type IV collagen 7s, APRI, FIB-4 index, and NFS as a marker of liver fibrosis in NAFLD patients." (PMID 27363523, 2016).
liver fibrosis (continued). "Elevated expression of the chemokine CCL20, macrophage inflammatory protein, that serve as chemoattractant for the immune cell’s infiltration to the injured hepatic tissues correlated to NASH and further play a key role in liver fibrosis in animal models." (PMID 41144456, 2025). "CCL20 is the primary ligand for the CC chemokine receptor 6 (CCR6) and serves as a chemoattractant molecule for immature dendritic cells, which have been shown to produce many of the inflammatory molecules that mediate liver fibrosis." (PMID 29690903, 2018).
Sepsis (14 papers, 2021 to 2025). Sepsis is defined as life-threatening organ dysfunction caused by a dysregulated host response to infection. "Infants who developed sepsis had higher levels of the proteins CCL20, CCL23 and CCL25 in infant plasma week 4 compared to infants who did not." (PMID 38001236, 2024). "The increased expression of CCL2 and CCL20 prevents pneumococcus-mediated sepsis in humans and mice (101, –, 103)." (PMID 36877045, 2023). "We demonstrated that combination of IL-8, IL-24 and CCL20 have the best value to identify NEC from sepsis or the severity of NEC." (PMID 36806964, 2023). "Further analysis showed the combination of IL-8, IL-24 and CCL20 have the best prediction value for NEC and control (AUC = 0.947), NEC and sepsis (AUC = 0.838) and different severity of NEC (AUC = 0.842)." (PMID 36806964, 2023). "The association between higher AF and lower levels of CCL20, CCL23 and CCL25 in infant plasma, and lower plasma levels in infants who did not develop sepsis support our hypothesis that AF may have protective properties." (PMID 38001236, 2024).
Arthritis (13 papers, 2011 to 2025). Inflammation of a joint. "Chronic inflammation and arthritis are associated with Prevotella, which induces inflammation by stimulating the production of IL-8, IL-6, and CCL20 through colonic epithelial cells." (PMID 34209270, 2021). "The interaction between CCR6 and CCL20 plays an important role in the migration of pathogenic Th17 cells in arthritis, and a majority of Th17 cells express CCR6." (PMID 25888974, 2015). "These potentially include NO production via rhythms in Nos2 expression and rhythmic MMP3 production, both previously linked to arthritis-associated joint damage and regulation of inflammation, as well as other inflammation-associated disease effectors (Cxcl5, Ccl20, Mmp13, Rankl/Tnfsf11)." (PMID 38981514, 2024). "Circulating CCL20 has been proposed as a biomarker of inflammation in various conditions, including neurological disorders, arthritis, and endotoxemia and hepatitis." (PMID 40646788, 2025). "In experimental studies of induced arthritis, myostatin regulates the recruitment of Th17 cells through increased levels of CCL20 on joint tissues, which subsequently induces an increase in IL-17 levels, contributing to the persistence of inflammation." (PMID 35592686, 2022). "Our integrative analyses of the transcriptome and methylome of synovial tissue from a murine arthritis model and patients with RA showed that CCL20 is a common UHRF1 target gene among cytokine-, RA-, and antiapoptosis-related genes." (PMID 35472067, 2022). "The receptors and their ligand CXCL13 and CCL20 have been suggested to be important for B-cell migration into the inflamed synovium in human arthritis, and CCR6 has been reported to be increased in peripheral B cells from arthritis patients." (PMID 31882654, 2019). "Migration of Th17 cells to the joints in arthritis is orchestrated mainly by CCL20 and corresponding receptor CCR6 expressed on Th17 cells." (PMID 25888974, 2015). "Taken together, these results support the contention that CXCL13 and CCL20, acting synergistically, may constitute a key driving force for the migration and recruitment of B lymphocytes in the inflamed synovium of patients with arthritis." (PMID 29880013, 2018). "Interestingly, we found increased Ccl20 mRNA in LNs from E2-treated mice with CIA day 14, revealing one possible mechanism for E2-induced retention of Th17 cells during arthritis development." (PMID 25888974, 2015). "MIP-3α/CCL20 can be detected in the synovium of RA patients, however, a possible role of MIP-3α/CCL20 in serum-induced arthritis has never been addressed." (PMID 22028860, 2011). "Based on CXCR5 and CCR6 internalization and B-cell migration experiments, our results suggest that CXCL13 and CCL20, the respective ligands of CXCR5 and CCR6, by acting synergistically, might participate in the recruitment of B cells in the synovium in patients with arthritis." (PMID 29880013, 2018).
diabetes (13 papers, 2013 to 2025). "Several studies based on preclinical and translational data predict the involvement of the CCL20/CCR6 axis in the development of diabetes and DKD, the leading cause of CKD." (PMID 41226600, 2025). "The primary aim of this study was to analyse plasma and urinary CCL20 levels in human CKD caused by diabetes or ADPKD, representing examples of kidney disease in response to systemic events and of a primary non-immune kidney disease, respectively." (PMID 41226600, 2025). "An observational study showed that CCL20 had a strong association with vascular endothelial inflammation, reflected systemic inflammation, and thus may become a potential biomarker of impaired vascular function in diabetes." (PMID 36158806, 2022). "The analysis showed that five SNPs were associated with diabetes: rs1024611 at the CCL2 gene locus, rs6749704 at CCL20, rs333 at CCR5, rs17366743 at ADIPOQ, and rs114758349 at TCF7L2." (PMID 36674502, 2023). "Studies have also reported that CCL20 is increased in pancreatic beta-cells undergoing inflammatory insults in developing diabetes." (PMID 24733189, 2014). "Our results demonstrate that blockade of KCa3.1 was able to attenuate the upregulation of CCL20 expression and macrophage infiltration induced by diabetes, which is mediated through inhibition of NF-κB activation." (PMID 24733189, 2014). "In addition, higher levels of the cytokine receptors, sIL-6R and sTNFR1, and the chemokines, CCL19, CCL20, CCL21, and CXCL11, were also associated with a history of self-reported diabetes at the <10% level." (PMID 28753646, 2017). "We observed associations between self-reported diabetes and the chemokines previously reported in the literature, including CXCL10 and interleukin-8 (IL-8), as well as identified a number of novel associations such as: CCL19, CCL20, CCL21, CXCL6, and CXCL11." (PMID 28753646, 2017). "We also found that diabetes was related to increased expression of nine proteins, IL-18R1, CCL11, CDCP1, OPG, HGF, TGF-α, CCL20, IL-6 and FGF-21." (PMID 34385358, 2021). "Afterwards, multiple linear regression analysis was performed in all patients, using plasma levels of CCL20 (logarithmic transformation to normalize the distribution) as the dependent variable and the presence of AAA, sex, diabetes, PAD, BVD and antiplatelet treatment as independent variables." (PMID 29229985, 2017). "Several predicted interactions were observed, many of them encompassing genes involved in the pathogenesis of diabetes, for instance miR-30e targeting IL1A and IRS2, miR-181a targeting IL1A, miR-223 targeting SLC11A2, miR-29b targeting ID1, miR-21 targeting CCL20, and many others." (PMID 24279768, 2013). "In Müller cells, FT011 reduced diabetes-induced gliosis and vascular endothelial growth factor (VEGF) immunolabeling and the hyperglycaemic-induced increase in ICAM-1, monocyte chemoattractant protein-1, CCL20, cytokine-induced neutrophil chemoattractant-1, VEGF and IL-6." (PMID 26222724, 2015).
viral infection (13 papers, 2011 to 2025). "In moderate-to-severe persistent asthmatics, viral infection was associated with increased protein abundance of CXCL10, IL-4, sICAM-1, CCL2, CCL20 and CCL24." (PMID 30463560, 2018). "In mild persistent asthmatics, viral infection was associated with increased protein abundance of CXCL10, sICAM-1, CCL2, CCL4, CCL5, CCL20 and CCL24." (PMID 30463560, 2018). "Including outliers yielded additional immune function–related genes, including those responsive to viral infection (CCL20, CXCR5, MX2), suggesting that these 2 samples may represent a more highly inflammatory state." (PMID 41212059, 2025). "In this study, the expression levels of the majority of genes involved in the TNF signaling pathway, including those encoding TNF, IL-6, CCL20, caspase 10, caspase 3, NF-κB, and TGF-β-activated kinase 1 (TAK1), were significantly downregulated after viral infection." (PMID 25423176, 2014). "Thus, due to the effect of virally induced Th1 cytokines, CXCL10 might predominate over CCL20 during BKPyV replication, indicating that different virus infections might indeed elicit different patterns of chemokine responses." (PMID 31981424, 2020). "The inflammatory cytokine CCL20 and the lung injury mediator PAI-1 are produced by the airway epithelium in response to allergy, viral infections and other inflammatory conditions (Gómez-Melero and Caballero-Villarraso, 2023; Morrow and Mutch, 2023)." (PMID 37680710, 2023). "After viral infections, immature LCs are recruited to the epidermis via chemokine (C-C-motif) receptor 6 (CCR6), which is the receptor for chemokine (c-c-motif) ligand 20 (CCL20) increasingly expressed by infected cervical keratinocytes." (PMID 36311788, 2022). "For FVC, statistically significant interactions between viral infection and inflammation were seen for CXCL10 mRNA, TLR3 mRNA, IL-4, IL-13, CCL5, CCL20 and CCL24." (PMID 30463560, 2018). "CCL20/MIP-3α is a strong chemotactic factor for lymphocytes, while a weak factor for neutrophils, that is upregulated by IFN-γ, tumor necrosis factor (TNF) and lipopolysaccharide, inducing a marked lung damage upon viral infection." (PMID 34851149, 2022). "In our longitudinal study, we found that, in the absence of viral infection, CXCL10, IL-4, IL-13, CCL4, CCL5, CCL20 and CCL24 were each negatively associated with FVC." (PMID 30463560, 2018). "For example, in the absence of viral infection, CXCL10 mRNA, MDA5 mRNA, CXCL10, IL-4, IL-13, CCL4, CCL5, CCL20 and CCL24 were negatively associated with FVC." (PMID 30463560, 2018). "Our results indicate that IEC might selectively regulate CCL20, CXCL10 and CCL5 in order to restrict the propagation of the viral infection and the subsequent tissue damage, thus promoting local clearance of the virus and facilitating re-establishment of tissue homeostasis." (PMID 36142892, 2022).